STAT3 (signal transducer and activator of transcription 3)
Diseases named in the same sentence as STAT3 in open-access papers (continued):
Sharing a sentence is not in itself a finding about the gene and the disease.
melanoma (continued). "More recently, an in silico study suggested that cryptotanshinone could affect both nuclear factor kappa B (NF-ҝB) and STAT3 signaling pathways in melanoma." (PMID 35163058, 2022). "Interestingly, we also found that WZB117 inhibited STAT3 phosphorylation in melanoma cells in a dose-dependent manner." (PMID 36188586, 2022). "Hence, the ONC-related downregulation of both STAT3 and Bcl2 can partially explain either the apoptosis induction or the reduction in colony formation found in soft agar with these two melanoma cell lines." (PMID 35742999, 2022). "To evaluate whether this enhanced IL-6 signaling mediated JAK1/2 activation, we blocked IL-6 and IL-6R with anti-IL-6 and anti-IL-6R antibodies, respectively, at concentrations that were sufficient to inhibit IL-6-induced p-STAT3 in melanoma cells." (PMID 36008408, 2022). "Importantly, the conclusions were made in melanoma model overexpressing the alternatively spliced, truncated isoform of STAT3 – STAT3β, which was believed to have dominant negative functions over the full length isoform." (PMID 35865518, 2022). "Because we have shown CDDO-Me-mediated attenuation of IL-6 production and STAT3 activation in melanoma-conditioned macrophages, we hypothesize that inhibition of JAK/STAT3 signaling is likely one of the mechanisms by which CDDO-Me inhibits tumor progression." (PMID 35265066, 2022). "However, comparable PKM2 expression in control versus EEF2K silencing cells and lack of interaction between EEF2K and PKM2 suggested that EEF2K increases the level of p‐STAT3 in a PKM2‐independent manner in melanoma." (PMID 35184394, 2022). "Furthermore, cilengitide decreased PD-L1 expression by reducing STAT3 phosphorylation in two melanoma cell lines." (PMID 35142593, 2022). "Activation of STAT3 has been noted as an important event in melanoma progression and metastasis." (PMID 35982955, 2022). "The extract of Sophorae Flos (SLE), Rosae Multiflorae Fructus, and Lonicerae Japonicae Flos (RLE) decreased STAT3 signaling activation by antagonizing p-STAT3 and resulted in an inhibitory effect on inflammatory cytokines, which finally exerted their effects on RA and melanoma." (PMID 36324680, 2022). "Furthermore, targeting PEAK1 significantly decreases EMT and metastasis in melanoma cells through inhibiting JAK/STAT3 signaling." (PMID 34365903, 2021). "The information reinforced that Tim-3 was mediated by stimulating TCR signaling to STAT3 pathways during PD-1 blockade in melanoma, providing further support for combination STAT3 inhibitor and anti-PD-1 therapy for patients suffering from melanoma." (PMID 33936081, 2021). "In several cancers including melanoma, STAT3 is a prognostic marker predicting poor outcomes." (PMID 34531850, 2021). "Recently, crosstalk between MAPK and JAK2/STAT3 pathways in melanoma cells has been revealed." (PMID 34201116, 2021). "The largest difference between the previous finding and ours was that our results revealed TRIM14 might mediate PTEN degradation to activate STAT3 pathway in melanoma." (PMID 33982666, 2021). "STAT3 has been shown to play a critical role in melanoma brain metastasis." (PMID 34691054, 2021). "Mechanistically, LRG1 mediates melanoma cell invasiveness in an EGFR/STAT3-dependent manner." (PMID 34208965, 2021). "Hence, a PD-L1 and/or STAT3 blockade with anti-PD-L1 or anti-STAT3 is considered as a potent treatment strategy in several cancers since the overexpression of PD-L1 and STAT3 is observed in melanoma, pancreatic, lung and other types of cancer cells." (PMID 34440920, 2021). "The phosphorylation of STAT3 at Tyr705 is positively associated with melanoma development and is a negative prognostic factor for overall survival of melanoma patients." (PMID 35096622, 2021).
melanoma (continued). "As the increases in STAT3 phosphorylation and AXL expression associated with a decrease in MITF expression have been associated with the resistance of melanoma cells to targeted therapies, we asked whether RICTOR/mTORC2 could play a role in resistance." (PMID 34680615, 2021). "Thus, nuclear p-CREB (Ser133), IL6 expression, and IL6/STAT3 signaling were all restored upon S100B knockdown in WM115 melanoma cells." (PMID 34411141, 2021). "Therefore, our work provides a potential therapy for STAT3 as a target in melanoma treatment, supporting combining anti-PD-1 and STAT3 antagonists as excellent therapy." (PMID 33936081, 2021). "Mechanistically, CD27-AS1-208 could directly interact with STAT3 and contribute to melanoma progression in a STAT3-dependent manner." (PMID 35096622, 2021). "We also found a negative association of CDK2/4/6/STAT3 SCNA with the various immune infiltration in melanoma." (PMID 33668805, 2021). "Furthermore, STAT3 activation is required for the promoting effect of LRG1 on melanoma cell migration and invasion." (PMID 34208965, 2021). "Altogether, these findings confirmed that targeting STAT3 could abrogate the immunosuppression of Treg cells, providing a potential target in melanoma treatment." (PMID 33936081, 2021). "In addition, PTEN/PI3K/AKT and STAT3 pathways participate in regulating TRIM14-induced melanoma development and progression." (PMID 33982666, 2021). "Targeting LRG1, therefore, may offer an alternative strategy to control STAT3-mediated melanoma metastasis." (PMID 34208965, 2021). "After confirming AKT and STAT3 pathways were associated with TRIM14-induced melanoma malignancy, we then further explored whether AKT or STAT3 pathway participated in regulating melanin synthesis of melanoma A375 cells mediated by TRIM14." (PMID 33982666, 2021). "Moreover, we have demonstrated that lncRNA CD27-AS1-208 was significantly up-regulated and exerted a facilitative role in melanoma progression through the activation of STAT3 pathway." (PMID 35096622, 2021). "Moreover, using Stattic to target the STAT3 pathway, we observed Tim-3 downregulation in in vitro phenotype and function assays and an in vivo melanoma model." (PMID 33936081, 2021). "Moreover, overexpression of PAX3 (paired box homeotic gene 3) or activation of STAT3 led to vemurafenib, a selective inhibitor of Braf, resistance in melanoma cells, and silencing of PAX3 and STAT3 reduced growth of vemurafenib resistance melanoma cells." (PMID 34577615, 2021). "In this study, we investigate whether NLRP3-dependent IL-1β production observed in melanoma cells drives IL-6/STAT3 signaling and whether this influences MDSC activity." (PMID 34531850, 2021). "As Lrg1-/- mice are healthy and have a normal life span, unlike mice treated with current STAT3 inhibitors, targeting LRG1 may cause fewer unwanted side effects and offers an alternative strategy to control STAT3-mediated melanoma metastasis." (PMID 34208965, 2021). "Indeed, this study demonstrated the role of STAT3 in the modulation of tumor-infiltrated Treg cells in vitro and in vivo melanoma mouse models." (PMID 33936081, 2021). "Besides, our results demonstrated that p-STAT3 in Treg cells upregulated after increased TGF-β production in animal models of melanoma after the PD-1 pathway blockade." (PMID 33936081, 2021). "Anti-IL-6 antibodies abolish STAT3 phosphorylation and block the proliferation of melanoma cells." (PMID 34356855, 2021). "Indeed, IL-17A promotes angiogenesis and induces IL-6 production in murine melanoma models, which in turn activates STAT3, upregulating the expression of angiogenesis and survival-supporting genes." (PMID 33466236, 2021). "Moreover, we also performed a flow cytometric analysis on Tim-3 on Treg cells upon depletion of STAT3 in melanoma tissues." (PMID 33936081, 2021). "Hence, to further explore the upstream mechanism that regulates STAT3 activation will facilitate the development of alternative approach for melanoma therapy." (PMID 35096622, 2021).
melanoma (continued). "Previous reports showed that cirsiliol induced radio sensitization in non-small cell lung cancer cell lines and inhibited interleukin (IL)-6-incuded STAT3 activation, and that cirsiliol could restrain the colony formation and migration of melanoma cells." (PMID 33731185, 2021). "However, when AKT or STAT3 pathway was blocked, levels of melanin synthesis of melanoma cells mediated by TRIM14 overexpression were decreased." (PMID 33982666, 2021). "In addition, PEAK1-induced effect in melanoma cells was reduced using U6 to inhibit JAK/STAT3 signal." (PMID 34365903, 2021). "STAT3 showed a high correlation with Treg cells in melanoma datasets." (PMID 33936081, 2021). "Similar to the results, we also found a slight decrease in Tim-3 expression in melanoma-infiltrated Treg cells, suggesting that inhibited STAT3 could abrogate Tim-3 expression in Treg cells." (PMID 33936081, 2021). "Conversely, nilotinib also suppresses the STAT3 pathways that can lead to a reduction in BCL2 expression that acts in concert with BIM induction to trigger an apoptotic response and cell death in KIT-mutated melanoma." (PMID 32344828, 2020). "In addition, our findings revealed that knocked down of Fyn decreased the phosphorylation of Stat3 in melanoma cells." (PMID 32565740, 2020). "Further studies are required for establishing the TLR4/STAT3/PU.1 loop in melanoma." (PMID 32312954, 2020). "Targeting STAT3 has been considered as a potential therapeutic strategy for melanoma treatment." (PMID 32536866, 2020). "Next we examined whether activation of STAT3 is required for TLR4 signaling-mediated melanoma progression in vivo." (PMID 32312954, 2020). "Whether TLR4 signaling activates STAT3 through the MYD88 and TRIF pathways in the two cancer types, as we observed in melanoma, and whether TLR4/STAT3 signaling plays a pathogenic role in the two cancers warrant further investigations." (PMID 32312954, 2020). "Therefore, we determined the effects of shikonin on the activation/phosphorylation of STAT3 in human melanoma cells." (PMID 32536866, 2020). "Data showed that shikonin treatment significantly reduced nuclear STAT3 levels in melanoma cells." (PMID 32536866, 2020). "We have observed that TLR4 ligands increase nuclear localization of STAT3 in melanoma cells." (PMID 32312954, 2020). "Moreover, we showed that NRASQ61 mutations have greater tumorigenic potential than NRASG12/13 both in immortalized melanocytes and in human melanoma cell lines through activation of the STAT3 pathway." (PMID 31906480, 2020). "Next, we examined whether inhibiting the TLR4/STAT3 pathway suppresses proliferation of melanoma cells in vitro and in vivo." (PMID 32312954, 2020). "As to melanoma, STAT3 activation plays a vital role in melanoma progression and metastasis." (PMID 32536866, 2020). "Moreover, in a mouse model, we demonstrated that STAT3 activation is required for TLR4 signaling-promoted melanoma progression in mice." (PMID 32312954, 2020). "We have shown that STAT3 activation is important for TLR4 signaling-mediated melanoma progression." (PMID 32312954, 2020). "We found that both LPS and MPLAs significantly increased cell proliferation and invasion in B16NC cells but not in B16STAT3β cells, suggesting a critical role of STAT3 activation in TLR4 signaling-caused melanoma progression." (PMID 32312954, 2020). "However, it displayed a pro-metastatic function in melanoma and stimulated cell migration by STAT3-mediated pathway." (PMID 32651426, 2020). "Moreover, the activation of Stat3 had also been abrogated both in Lj-1-60 treated melanoma cells or Fyn knocked down cells." (PMID 32565740, 2020). "We conclude that the inhibition of the STAT3 upstream regulator HER might help to overcome melanoma therapy resistance toward targeted therapies." (PMID 33327495, 2020).
melanoma (continued). "Second, we found that TLR4 ligands activate STAT3 through MYD88 (myeloid differentiation primary response gene 88) and TRIF (TIR-domain-containing adapter-inducing interferon-β) in melanoma cells and promote STAT3-mediated cellular events in melanoma progression." (PMID 32312954, 2020). "Next, we examined whether activation of STAT3 is required for the cellular events in TLR4 signaling-mediated melanoma progression." (PMID 32312954, 2020). "In conclusion, activation of STAT3 is a key event in TLR4 signaling-mediated melanoma progression." (PMID 32312954, 2020). "In addition, exosomal miR-155 derived from melanoma cells upregulated the expression of proangiogenic factors, such as VEGF, FGF2, MMP9, in CAFs by targeting SOCS1/JAK2/STAT3 signaling pathway, which resulted in the increase of melanoma angiogenesis." (PMID 32489584, 2020). "We next determined the effects of shikonin on STAT3-targeted molecules in human melanoma cells." (PMID 32536866, 2020). "STAT3 is a well-established target in experimental melanoma treatment." (PMID 32312954, 2020). "Here, we examined whether TLR4 ligands affect melanoma progression-related genes that can be transcribed by STAT3 in melanoma cells." (PMID 32312954, 2020). "Melanoma cell lines stably depleted of STAT3 were established with lentiviral constructs." (PMID 31192135, 2019). "More recently, we used the same NP to encapsulate S3I-1757, a newly developed STAT3 inhibitor with higher potency and specificity, and we found that this NP (i.e., S3I-NP) demonstrated significant therapeutic efficacy against melanoma in a SCID mouse xenograft model." (PMID 30791634, 2019). "In conclusion, these results indicate that in melanoma cells, the STAT3 signalling protein is a target of the (Bu2Sn)2TPPS and (Bu3Sn)4TPPS that could mediate the inhibition of melanoma proliferation and metastatic dissemination weakened by these complexes." (PMID 31801187, 2019). "However, in human melanoma cells where STAT3 is persistently activated, the STAT3-NFκB-p300 protein complex can cooperatively activate the expression of many oncogenic/inflammatory genes." (PMID 31474976, 2019). "Co-delivery of imatinib and anti-STAT3 siRNA (non-invasive topical iontophoretic administration) using gold NPs is related to a remarkable decrease in tumor volume and tumor weight in melanoma tumor bearing mice, showing the efficacy of gold NPs in treatment of melanoma by inhibition of STAT3." (PMID 31569687, 2019). "Recently, Tournier’s group demonstrated that selective ERK5 ablation in macrophages blocks phosphorylation of signal transducer and activator of transcription 3 (STAT3), a transcription factor crucial for macrophage polarity, impairing the growth of melanoma and carcinoma xenografts." (PMID 30901834, 2019). "Moreover, we found that STAT3 bound to the PD-L1 promoter in melanoma cells, and knocking down α9-nAChR expression inhibited STAT3 binding to the PD-L1 promoter, leading to PD-L1 downregulation." (PMID 31835799, 2019). "With respect to its ability to promote cancer through regulating cancer stem cell (CSC) activities, STAT3 upregulation mediates reprogramming of melanoma cells to melanoma stem cells by inducing expression of the Yamanaka factors, providing hints of STAT3 implication in cancer stemness." (PMID 31569642, 2019). "Having shown that pharmacological inhibition of STAT3 affects NDV/FMW-mediated cell death in melanoma cells, we asked whether STAT3 inhibition could exert effects on NDV/FMW-induced ICD markers." (PMID 31192135, 2019). "Oc could inhibit signal transducer and activator of transcription 3 (STAT3) signaling pathway, involved in apoptosis, invasion and angiogenesis of melanoma cells, and also the tumor growth and metastasis of melanoma in vivo." (PMID 31137753, 2019).
melanoma (continued). "Moreover, STAT3 increases chemoresistance of melanomas to selective inhibitors of BRAF, which are exploited in the treatment of unresectable or metastatic melanoma with a BRAF-V600 gain-of-function mutation." (PMID 31569642, 2019). "Upregulation of key cancer-related inflammation genes, such as the transcription factors nuclear factor ‘kappa-light-chain-enhancer’ of activated B-cells (NF-κB) and STAT3, as well as several inflammatory cytokines and angiogenic factors, facilitate melanoma development." (PMID 31569642, 2019). "Given that Th17 and Tregs have been found dysregulated during melanoma progression, it is appealing to postulate that disturbance of the Th17/Treg homeostasis may favor melanoma cell proliferation in a STAT3/STAT5-dependent manner." (PMID 31569642, 2019). "Thus, WP1066 (an inhibitor of STAT3 signaling) enhances T-cell cytotoxicity against melanoma through inhibition of FOXP3+ Tregs." (PMID 31480382, 2019). "We also show that STAT3 plays a role in NDV/FMW-induced ICD in melanoma cells." (PMID 31192135, 2019). "Since dacarbazine has been shown to promote a relatively weak apoptotic response in melanoma we speculated that combining this cytotoxic insult with STAT3 silencing could be a good model to assess the contribution of the STAT3/PDK1 pathway on cell death." (PMID 30622697, 2019). "The crosstalk between microglia and melanoma BrM is evident from the alteration of JNK and p38 components in microglia, which may attenuate their phagocytic response, as well as ERK and STAT3 in melanoma cells, which are linked to angiogenesis." (PMID 31396225, 2019). "The constitutive activation of STAT3 has been reported in melanoma patients." (PMID 30691132, 2019). "Together, these results indicate that nicotine-induced α9-nAChR activity activates the STAT3 signaling pathway that influences melanoma cell proliferation and upregulates PD-L1 expression, and the STAT3 inhibitors Stattic and NSC74859 prevent nicotine-induced PD-L1 expression and proliferation." (PMID 31835799, 2019). "One study shows that STAT3/IRF1 are required for PD-L2 expression in melanoma cells." (PMID 31480382, 2019). "Moreover, NDV/FMW-induced ICD markers in melanoma cells were also suppressed by either treatment with a STAT3 inhibitor or shRNA-mediated depletion of STAT3." (PMID 31192135, 2019). "STAT3 also has an important role in melanoma development and survival." (PMID 30691132, 2019). "Both HDAC6 and STAT3 are recruited to the PD-L1 gene promoter in melanoma." (PMID 31258527, 2019). "Similarly, combined knockdown of c-Jun and STAT3 genes in the same melanoma model showed a synergistic effect on PD-L1 downregulation." (PMID 29765155, 2018). "With the aim to test the hypothesis of topical siRNA targeting STAT3 as a gene therapy strategy for melanoma, we developed for the first time a novel intradermal delivery system for STAT3 siRNA based on dissolving MNs." (PMID 29348670, 2018). "Interestingly, the overexpression of STAT3 would at least partly reverse the anti-cancer effect of ATL-I on melanoma cells." (PMID 30505341, 2018). "Moreover, hyperactivity of STAT3 in melanoma increases the expression of VEGF to induce angiogenesis." (PMID 29348670, 2018). "Gene therapy applying siRNA targeting STAT3 is a potential therapeutic strategy for melanoma." (PMID 29348670, 2018). "The results might be attributed to the targeting delivery of STAT3 siRNA to melanoma via dissolving MNs and the selective effect of STAT3 siRNA on STAT3 gene of melanoma cells." (PMID 29348670, 2018). "Also, STAT3 promotes growth of advanced melanomas and up-regulates the activity of vascular endothelial growth factor (VEGF) and basic fibroblast growth factor (bFGF) in these cells, suggesting its role in angiogenesis." (PMID 30166456, 2018). "Moreover, activated STAT3 in melanoma can directly combine to matrix metalloproteinase-2 (MMP-2) gene promoter to increase the expression of MMP-2." (PMID 29348670, 2018).